CCND2 (cyclin D2)
Diseases named in the same sentence as CCND2 in open-access papers (continued):
Sharing a sentence is not in itself a finding about the gene and the disease.
tumor (continued). "However, a negative and significant correlation between PICOT and CCND2 mRNA levels was only observed for 8 out of the 32 tumor types considered." (PMID 31527584, 2019). "Besides, we also found that miR-146a-5p could inhibit tumor growth in xengroft mouse models, and CCND1 and CCND2 were downregulated in miR-146a-5p overexpressed xengroft tumor tissues." (PMID 27494902, 2016). "CCND2 was not methylated in any of the tumor-adjacent or tumor-distant tissues." (PMID 26370119, 2015). "Epidermal growth factor receptors (EGFR) suppress the tumor suppressors miR-143 and miR-145, which coordinately control multiple targets of downstream cell-signaling pathways (i.e., K-Ras or MYC, cdk6, E2F3, and G1/S-specific cyclin-D2 or CCND2) in the AOM rodent model." (PMID 23060898, 2012). "Although various genes such as ADCYAP1, HAND2, MME, and RASSF1A have been reported to exhibit abnormal methylation and tumor development in UCEC, the role of CCND2 gene methylation in UCEC has not been reported." (PMID 40678058, 2025). "In an analysis of 80 paired tumor and adjacent nontumor tissue samples, FGF9 and CCND2 expressions were significantly elevated in tumor tissues compared to adjacent nontumor tissues." (PMID 30227870, 2018). "We are first to report that in PTSMTs, a non-canonical activation of WNT, independent of beta-catenin, drives tumor cell proliferation via MTOR/AKT1, MYC and Cyclin D2." (PMID 29881541, 2018). "For the remaining genes (SSBP2, MCAM, ERα, ERβ, CCND2, MGMT, GSTP1 and p16) methylation in serum DNA was always corresponding to methylation of tumor DNA, while methylation of tumor DNA was not always corresponding to methylation of serum DNA." (PMID 28147335, 2017). "Consistently, the transcription of WNT5A and CCND2, but not CCND1, was also elevated in PIAS1 knockdown xenograft tumor samples." (PMID 24586797, 2014). "We tested the promoter methylation of CCND2, CCNA1 and CALCA in urine sediment DNA from primary UCC cases and subjects without any neoplastic disease (controls/normals)." (PMID 24980822, 2014). "Additionally, the involvement of GLI1 downstream target genes such as PTCH1, Cyclin D2, Plakoglobin, NKX2.2 and PAX6 have not been studied in either tumor." (PMID 21059263, 2010).
cancer (229 papers, 2003 to 2025). A tumor composed of atypical neoplastic, often pleomorphic cells that invade other tissues. "Cyclin D2 (CCND2), a core component of cell cycle machinery, influences the growth and proliferation of cancer cells and is associated with tumorigenesis." (PMID 40236693, 2025). "For instance, the expression of FoxO4 protein induced cell cycle arrest in p27‐deficient cells by inhibiting cyclin D2, demonstrating the physiological relevance of carotenoids‐activated, FoxO‐induced cell cycle arrest in the treatment of cancer." (PMID 40161411, 2025). "Similar to the p27Kip1 protein, a number of SNPs of the CCND2 gene located on chromosome 12p13.32 encoding cyclin D2 have been studied and found to be associated with the regulation of cyclin D2 protein expression and susceptibility to cancers." (PMID 39519258, 2024). "Our results suggest that PRRC2B promotes cell proliferation by facilitating the translation of CCND2 mRNA, which encodes the D-type cyclin facilitating G1/S transition in cancer and stem cells." (PMID 37125639, 2023). "This is in tandem with findings from previous studies that concluded that hypermethylation of CCND2 is associated with the progression of various cancers." (PMID 35155426, 2022). "The hyperactivity of CCND2 has been associated with malignancy, and it promotes proliferation in cancer cell lines." (PMID 36245757, 2022). "Methylation of promoter region mediated silencing of CCND2 expression associated with a few cancer types progression is also reported." (PMID 35845108, 2022). "CCND2 plays a critical role in cell cycle regulation where it was reported that overexpression of CCND2 in cancer cells is associated with enhanced cell proliferation and aggressiveness." (PMID 34044804, 2021). "CD155 played a vital role in increasing cell proliferation in ras-mutated cancer cells, by upregulating cyclin D2, activating of ERK signal, downregulating p27, and shortening the G0/G1 phase of the cell cycle." (PMID 32411795, 2020). "In a randomized placebo-controlled clinical study in women with high breast cancer risk, the effects of RES on the expression of some cancer-related genes, such as CCND-2, p16, RASSF-1α, and cancer-promoting prostaglandin E2 (PGE2), were assessed." (PMID 33202681, 2020). "Due to the fact that contradictory results of prognosis value or expression of CCND2/3 exist in various tumors, a meta‐analysis for CCND2/3 prognostic role in multiple human malignant neoplasms need to be conducted to clarify the real association." (PMID 30950241, 2019). "Reduced CCND2 expression has been reported in various cancers, and the mechanism underlying CCND2 silencing in these cases was aberrant promoter methylation." (PMID 30308939, 2018). "The demethylating agent antroquinonol D upregulated CCND2 expression, caused cell cycle arrest, and inhibited cancer cell growth and migration ability." (PMID 30308939, 2018). "The enrichment of the super-enhancer markers exceeded that of known cancer-associated super-enhancers within the CCND2 and FOSL1 gene loci." (PMID 27624132, 2016). "As the regulatory subunits of CDK4 or CDK6, CCND1 and CCND2 are required for cell cycle G1/S transition, and thus have been implicated as proto-oncogenes and attractive targets for cancer therapy." (PMID 27494902, 2016). "Silencing of expression of cyclin D2 through promoter hypermethylation is associated with cancer progression and aggressiveness in breast, lung, pancreatic and gastric cancers." (PMID 26703571, 2015). "The most upregulated cyclin was CCND2, which is implicated in cell differentiation and malignant transformation and is inactivated by promoter hypermethylation in several types of human cancer." (PMID 24932297, 2014).
cancer (continued). "The dysregulation of CCND2 activity was implicated in multiple cancers, including CRC." (PMID 35033075, 2022). "Cyclin-D2 (CCND2) is ubiquitously implicated in cancer uncontrol cell proliferation." (PMID 35306579, 2022). "In addition, Ccnd2, Ccnd1, and Raf1 are targets of the downregulated miR-15b-5p in exposed mice, and these targets are implicated in cancer and cell cycle regulation." (PMID 34199666, 2021). "CCND2, a member of the D-type cyclins has been implicated in cell cycle regulation, differentiation and malignant transformation, and is seemingly inactivated in human cancers." (PMID 32784654, 2020). "Indeed, reduced expression of CCND2 has been reported in various cancers and the mechanism underlying CCND2 silencing in these mentioned cases is the aberrant promoter methylation." (PMID 27583477, 2016). "Recent reports indicated that CCND2 polymorphisms are associated with human cancer risk, thusly we hypothesized that CCND2 gene polymorphisms may contribute to childhood ALL susceptibility." (PMID 24743557, 2014). "This risk-stratified progression in lung tissues suggests that CCND2 hypermethylation may truly reflect an early precancerous change in the lung, en route to overt cancer, which may be due to the effects of smoking." (PMID 21577262, 2011). "In addition, expression levels of cell cycle (CDK2, CDC2, CCND2) and inflammation markers linked to cancer (NOS2, TGFβ1, CHI3L1 and TFPI) were significantly increased in Caco-2WT/miR-373 compared with Caco-2WT/miR-c, but decreased in Caco-2D299G/α-miR-373 compared with Caco-2D299G/α-miR-c." (PMID 27271572, 2016). "Only 6 CDGs appeared under cell cycle and those were ANAPC13, ANAPC5, MAD2L2, GADD45G, CCND2, and surprisingly MYC — a gene often implicated as a cancer driver." (PMID 39774001, 2025). "Loss of the miR-26 family has been described in EC and other cancers, where it relieves cell cycle and epigenetic checkpoints through targets such as CCND2 and EZH2." (PMID 41226475, 2025). "The canine overexpression of CCND2 concurs with other studies as this oncogene is overexpressed in numerous cancer types." (PMID 40566602, 2025). "The CCND2 gene, located on chromosome 12, played a crucial role in the PI3K-Akt signaling pathway and was closely associated with the development of cancer." (PMID 40678058, 2025). "Beyond the recurrent amplification of CCND1, CCND2, CDK4, MDM2, and MYCL1, chromothriptic chromosomes were associated with the amplification or loss of other well-established cancer genes." (PMID 39185963, 2025). "We found that in a significant percentage of human CRC tissue samples, cyclin D2 is expressed at high levels in the nuclei of cancer cells." (PMID 39513917, 2024). "Mechanistically, STAT3 binds to the cyclin D2 (CCND2) promoter, increasing its transcription and sustaining cancer stem cell growth post-radiotherapy by maintaining cell cycle integrity and reducing DNA damage accumulation." (PMID 39335624, 2024). "The R24C mutation prevents INK4-family CDK4 inhibition; in cancers, Cdk4-R24C mutation is synergistic with loss of function of Cip/Kip inhibitors, suggesting that Cdk4-R24C may counteract a damaging combination of loss of cyclin D2 with gain of p27 in IRS2 null β cells." (PMID 37712417, 2023). "CCND2 expression was increased in all cell lines with a higher increase in cancer cell lines (>7–15 fold) compared with CSC‐treated Beas‐2B cells (>5–6 fold)." (PMID 36621828, 2023). "Low expression of cell cycle protein D2 (CCND2) has been reported to promote cancer cell growth, leading to poor patient prognosis." (PMID 36673982, 2023). "It remains unclear why the loss of CCND2, and, therefore, CCND2-associated cell proliferation, is observed in cancers, but this may be due to a compensation effect leading to the up-regulation of another cyclin, e.g., cyclin E. Another explanation may be related to the stage or sub-type of cancer." (PMID 37510349, 2023).
cancer (continued). "Among them is cyclin D2, which can be either overexpressed or under-expressed, depending on the type of cancer." (PMID 37568789, 2023). "While its roles in development have only recently been discovered, the role of CCND2 in cancers is more established." (PMID 37510349, 2023). "Conversely, in GCB cell lines NU-DHL-1 and SU-DHL-6, amplification of cyclin proteins CCND2 and CCND3 oncogenes were found to be associated with uncontrolled growth of cancer cells." (PMID 36831263, 2023). "FOXO1 regulates the expression of a number of cancer-related genes, such as p27KIP1, p21WAF1, cyclin D1, cyclin D2, FasL, p130, and Bim." (PMID 36293387, 2022). "ZKSCAN3 enhances the expression of a variety of target genes involved in cancer cell proliferation (cyclin D2), growth (IGF-2, integrin β4), metastasis (MMP26), and angiogenesis (VEGF)." (PMID 36012568, 2022). "Independent confirmation of the significance of CCND2 came from the Cancer Dependency Map project, where genome-wide RNAi screens identified CCND2 as an essential gene in the two 2 RUNX1/RUNX1T-expressing AML cell lines within a total of 501 cancer cell lines." (PMID 33217477, 2021). "The CCND1 is always overexpressed in cancer and regulates cell cycle transition from G1 phase to S phase along with CCND2 and CCND3." (PMID 34627268, 2021). "We showed a novel molecular mechanism underlying the specific interaction of the pro-tumorigenic FBXL8 with two cancer suppressors, CCND2 and IRF5, resulting in their downregulation." (PMID 32784654, 2020). "Typically, in human cancers, cyclin D1 is aberrantly expressed at much higher levels than cyclin D2 or D3." (PMID 32337233, 2020). "The prognostic role of CCND2 has been frequently reported in many cancer types, though effects are context specific." (PMID 33027769, 2020). "CCND1 is more frequently dysregulated in human cancers and therefore more studied than cyclin D2 or D3." (PMID 32013938, 2020). "On the other hand, according to the catalog of somatic mutations in cancer (COSMIC), PC9 cells harbor mutations in the genes encoding such key regulators of cell cycle progression as CCND2 and CDKN2A." (PMID 32183160, 2020). "NR4A1 is found to be overexpressed in numerous cancers, leading to increased proliferation and survival in these cancer cells via upregulating some target genes, including cyclin D2, E2F1, and survivin." (PMID 33328994, 2020). "These factors, produced by amniotic stem cells, can regulate the expression of cancer cell proteins associated with the cell cycle, such as cyclin-dependent kinases (CDK2, CDK4, CDK6) and cyclins (cyclin D2, cyclin E1, cyclin H)." (PMID 32972410, 2020). "Of significance is that FBXL8 is a specific protein degradation enzyme which selectively targets cancer suppressors like CCND2 and IRF5." (PMID 32784654, 2020). "Knockdown of CCND2 has been reported to increase the growth rate and migration ability of cancer cells." (PMID 32784654, 2020). "Downregulation of JAK2/STAT3/CCND2 signaling to sensitize cells to radiotherapy and impair cancer stemness." (PMID 32872659, 2020). "CCND2, a crucial cell cycle-regulatory, PCa-related gene, was identified as aberrantly expressed in PCa and many other cancers to regulate cancer cell growth." (PMID 32784653, 2020). "The network revealed that CRC-related DERs such as hsa-miR-1-3p, hsa-miR-490-3p, hsa-miR-542-5p, hsa-miR-424-5p, and hsa-miR-133a-3p are associated with the regulation of several cancer-related pathways by targeting TIMP3, FOS, PPP1R12B, CCND2, and EGFR." (PMID 32153636, 2020). "Our results indicated CCND2/3 played an oncogenic role in all of the cancer patients (CCND2: pooled HR = 2.21, 95% CI: 1.67‐2.93; CCND3: pooled HR = 2.29, 95% CI: 1.05‐5.03)." (PMID 30950241, 2019). "After deleted the data, the results indicated CCND2‐positive expression was an important adverse predictor of OS in cancer patients (pooled HR = 2.21, 95% CI: 1.67‐2.93, P = 0.799)." (PMID 30950241, 2019).
cancer (continued). "CCND2 gene has been shown to be targeted by expression of mir-4317 and miR-671-3p and related to inhibition of cancer progression in NSCLC." (PMID 31027181, 2019). "Using the Pearson’s correlation coefficient, we examined the extent of correlation between PICOT and CCND2 in each cancer, after clipping the top and bottom decile of each measurement to avoid outlier effects." (PMID 31527584, 2019). "Resveratrol was administered twice daily for twelve weeks and the focus was on the DNA methylation of four cancer-related genes—p16, Ras Associated Domain family-1α (RASSF-1α), Adenomatous Polyposis Coli (APC) and Cyclin D2 (CCND2)." (PMID 30781847, 2019). "The associations between CCND2/3 and prognostic outcomes (OS, DFS/RFS/PFS) of patients with various cancers were explored systemically." (PMID 30950241, 2019). "Considering these limitations, our results should be interpreted rigorously, and more attention should be paid to the function of CCND2/3 in various carcinomas in large multicentric studies." (PMID 30950241, 2019). "The cell model assay indicated that CCND2 expression inhibited cancer cell growth and migration ability." (PMID 30308939, 2018). "Antroquinonol D induces CCND2 DNA demethylation, recovery of CCND2 expression, cancer cell death, and metastasis inhibition." (PMID 30308939, 2018). "Cyclin Ds that contain Cyclin D1, Cyclin D2 and Cyclin D3, are closely related G1 cyclins and are of particular importance to the cancer field." (PMID 29041983, 2017). "Further, it has previously been linked to the development of cancer, and is involved in the proliferation and survival of cancer cells through its direct involvement in the regulation of cyclin D2 (CCND2), p19 and Fas." (PMID 25803042, 2015). "In accordance with these results, our study showed that cyclin D1 and cyclin D2 are also up-regulated in the majority of human primary lung tumors and cancer cell line (A549 and SK-MES-1)." (PMID 26325180, 2015). "CCND2 expression is shown to increase as progression of stages of malignant tumors, with the highest activities was observed in metastatic lesions." (PMID 26393798, 2015). "This novel finding suggests that USP22 promotes cell proliferation via the c-Myc/cyclin D2 pathway, leading to cancer development." (PMID 24466336, 2014). "We examined the transcriptional relationship in the BMI-1, p14ARF, c-Myc and cyclin D2 expression by quantitative real-time PCR in the ACC-83 cancer cells." (PMID 24466336, 2014). "In SK-TRb cells, T3 down-regulated mRNA levels of Ccnd2, Cdk6, Cdc25, E2f3, c-Myb, Wee1 and Chk1 involved in cell proliferation and cancer." (PMID 24796297, 2014). "CCND2 and CCND3 genes and their encoded proteins are also overexpressed in many cancer cases in humans." (PMID 25304455, 2014). "This ongoing study explored the association of CCND2 rs3217927 polymorphism in 753 newly diagnosed childhood ALL patients and 1088 cancer-free controls." (PMID 24743557, 2014). "By contrast, cyclin D2 was expressed in all the carcinoma and matched normal tissues with the expression levels being higher in the carcinoma tissues." (PMID 24765199, 2014). "This is a unique feature among the three closely related D type G1 cyclins (D1, D2 and D3), as amplification of cyclin D2 and D3 copy-number is rarely observed in human cancer." (PMID 23786849, 2013). "Cyclin-D2 methylation was found only in patients with IC type of cancer (P = 0.0017 vs. IA+ IB; P = 0.0088 vs. IA and P = 0.011 vs. IB)." (PMID 15574200, 2004).